MYB (MYB proto-oncogene, transcription factor)
Diseases named in the same sentence as MYB in open-access papers (continued):
Sharing a sentence is not in itself a finding about the gene and the disease.
tumor (continued). "Furthermore, immunostaining shows that the tumor tissue is MYB, CD43, and CD117 negative." (PMID 31912868, 2020). "When cells were implanted subcutaneously into the flanks of mice, the efficiency of tumor growth formation was comparable between parental, MYBwt and MYB-NFIB cells, suggesting that MYB-NFIB expression by itself does not enhance tumor growth activities." (PMID 35565392, 2022). "Transcriptional regulation of the MYB gene has not been studied in detail in ACC tumors, but in most tissues and tumor types, transcription of the gene initiates upstream of exon 1 at the normal promoter, designated here as TSS1 (Transcription Start Site 1)." (PMID 31877778, 2019). "However, patients with MYB-NFIB expressing ACC showed increased tumor vascularization and VEGF production compared with non-expressing patients, indicating a considerable pro-angiogenic effect of MYB-NFIB in ACC." (PMID 38835346, 2024). "Although the primary patients’ tumor samples referenced in this report were no longer accessible for analysis, one of the patient-derived xenografts utilized in this study (ACCX20M1) represented a case of MYB-NFIB fusion with the MYB exon 8 breakpoint." (PMID 35565392, 2022). "However, the mechanisms regulating c-MYB activity and the function of c-MYB in normal and tumor cells is not completely defined." (PMID 30781655, 2019). "4EGI-1 treated tumor cells presented decreased CSC pluripotency markers NANOG and OCT4, tumor metastasis regulator CXCR4, EMT mediator c-MYB and proangiogenic factor VEGF, but not translation initiation factors eIF1A or eIF5, comparing to vehicle treated breast CSC tumor cells in vivo." (PMID 25115391, 2014). "To test if MYB fusion-negative ACC tumors exhibit a different downstream gene expression profile, we initially pre-selected 6 fusion-positive and 6 fusion-negative ACC tumor samples scored by RT-PCR." (PMID 25587024, 2014). "Additionally, expression of GATA binding protein 3 (GATA3), which encodes a trans-acting T-cell specific transcription factor protein, was significantly decreased in the MYB-NFIB fusion sample (RPKM was 601 in fusion sample, 13072 on average in no-fusion tumor samples)." (PMID 29299133, 2017).
cancer (193 papers, 2001 to 2026). A tumor composed of atypical neoplastic, often pleomorphic cells that invade other tissues. "Among these 11 SEs, only the SEs associated with KLF5 and MYB were located within the genomic regions showing recurrent duplication, as observed in a high-resolution whole-genome sequencing dataset from the Pan-Cancer Atlas of Whole Genomes (PCAWG) Project." (PMID 40234694, 2025). "In fact, MYC expression is tightly regulated by MYB proteins, which highlights one important aspect of the manifold roles of MYB proteins in cancer-associated processes." (PMID 38835346, 2024). "The consideration of MYB-associated mechanisms for anticancer drug development will likely improve the therapy options for cancer patients in the future." (PMID 38835346, 2024). "MYB, a proto-oncogene encoding a transcription factor, is involved in the regulation of several cancer-associated genes." (PMID 38089573, 2023). "On the contrary, lower expression of MYB was significantly associated with a poorer outcome in four cancers including STES, STAD, HNSC and READ." (PMID 36994664, 2023). "Among the 44 types of cancer, we found that the top three tumors with the most significant association between MYB expression and immune score were KIPAN, KIRC and BRCA." (PMID 36994664, 2023). "MYB is able to decrease apoptosis and promote cancer cell survival through (vi) upregulation, which encodes proteins belonging to the BCL-2 family." (PMID 37511133, 2023). "MYB is highly expressed in thymocytes and MYB is often dysregulated in cancer and thus this mutation can lead to robust TAL1 transcription in leukemic cells." (PMID 35514954, 2022). "This study has successfully identified high-risk pathogenic nsSNPs in the MYB oncoproteins towards understanding its association with human cancer using an in-silico approach." (PMID 34921182, 2021). "MYB encodes a transcription factor that plays key roles in normal function and cancers of the hematopoietic system, mammary and colonic epithelium and certain other tissues." (PMID 26812885, 2016). "Sensitizing effects and synergies were documented for combinations of MYB-targeting drugs with currently applied cancer therapeutics such as cisplatin, doxorubicin, and imatinib, which underline the potential of MYB inhibitors as promising anticancer drug candidates." (PMID 38835346, 2024). "The MYB transcription factors are a point of convergence of numerous signalling pathways essential for multiple cellular functions, and their deregulation has been associated with aggressive behaviour of cancer cells." (PMID 33637673, 2021). "By further focusing on the role of miRNA, new treatment strategies could be found to overcome cancers associated with elevated MYB." (PMID 34876130, 2021). "MYB encodes for a transcription factor that is a key regulator of hematopoietic cell proliferation and deregulated MYB activity has been observed in variety of human cancers." (PMID 29654229, 2018). "But mutations in the normal MYB gene have also been found in several types of human cancer." (PMID 25279451, 2014). "This has led, to the hypothesis that aberrant activation of vertebrate MYB could also cause cancer." (PMID 34876130, 2021). "This led to the hypothesis that aberrant activation of vertebrate MYB could also cause cancer." (PMID 33637673, 2021). "For example, the TAF12/TAF4 histone-fold heterodimer binds to the activation domain of MYB and protects MYB from degradation in cancer cells." (PMID 41028714, 2025). "We also found MYB-SE is frequently duplicated in gastrointestinal adenocarcinoma in comparison to other cancer types." (PMID 40234694, 2025). "The PI3K‐Akt signaling pathway plays a key role in cell growth, survival, metabolism, and motility, and activation of its related genes (MYD88, IL7R, MYB, CSF1) has been implicated in the initiation and progression of several cancers." (PMID 41328768, 2025).
cancer (continued). "Although duplications containing MYB-SE were found in many cancer types, MYB-SE duplication occurs more frequently in gastrointestinal adenocarcinoma (Fig. EV1D)." (PMID 40234694, 2025). "MYB (MYB proto-oncogene) is a transcription factor known to play a role in various cancers, including TNBC, where it often contributes to cell proliferation, survival, and therapy resistance." (PMID 41141380, 2025). "Among the TNBC lines, MDA-MB-231 cells exhibited the highest MYB expression (p=0.02 versus BT-549), suggesting a potential correlation between MYB overexpression and aggressive cancer phenotypes." (PMID 41141380, 2025). "We next analyzed the chromatin landscape using the Assay for Transposase-Accessible Chromatin with high throughput sequencing (ATAC-seq) of patient samples and H3K27ac ChIP-seq of COREAD and STAD cancer cell lines with high or low MYB expression." (PMID 40234694, 2025). "Various types of genomic alterations at the MYB locus have been detected in human cancer, such as duplication, translocation, gene-fusion, and intragenic mutations." (PMID 40234694, 2025). "In contrast, MYB-low cancer cell lines showed minimal enrichment of H3K27ac signals in the candidate MYB-SE region." (PMID 40234694, 2025). "We found that the candidate MYB-SE region exhibited a chromatin-accessible state, and MYB-high cancer cell lines displayed strong H3K27ac signals in this region." (PMID 40234694, 2025). "This binding pattern of HIF1α and MYB was confirmed by ChIP-qPCR assay on select sites in additional cancer cell lines." (PMID 40680814, 2025). "NO released by nitroprusside induced differentiation in MYC-dependent HL-60 AML cells and apoptosis in NA epithelial cancer cells by suppression of MYB and MYC." (PMID 38835346, 2024). "Taken together, studies on the role of MYB proteins on cancer resistance to tubulin-targeting drugs are scarce and under-represented." (PMID 38835346, 2024). "This review describes the correlation of MYB transcription factors with the formation and persistence of cancer resistance to various approved and investigational anticancer drugs." (PMID 38835346, 2024). "Antisense drugs targeting non-coding RNAs and miRNA-based drugs are also promising strategies to suppress MYB in cancers." (PMID 38835346, 2024). "Several multi-kinase inhibitors were clinically studied in aggressive and therapy-resistant cancers with altered MYB (e.g., ACC) and revealed controversial outcomes." (PMID 38835346, 2024). "Many key questions remain unresolved regarding the application of MYB inhibitors in human cancer patients and their potential side effects." (PMID 38542205, 2024). "In conclusion, diverse approaches have been instrumental in identifying potential MYB inhibitors, offering promising avenues for therapeutic interventions in various cancers, particularly AML, T-ALL and ACC." (PMID 38542205, 2024). "Cancer stemness, angiogenesis, and autocrine/paracrine signaling by upregulation of growth factors are also promoted by MYB proteins." (PMID 38835346, 2024). "To evaluate the potential impact of BUB1 inhibition in MYB‐driven cancers, we treated MM MYB cells with BAY1816032, a selective inhibitor of the catalytic activity of the kinase." (PMID 38112379, 2024). "These proteins can sustain cancer cell growth under adverse conditions and confer resistance to treatment, making MYB a potential therapeutic target in cancer treatment." (PMID 39139556, 2024). "Further research along these lines will deepen our comprehension of MYB’s function in human malignancies and, optimistically, yield compounds suitable for the therapeutic intervention in these cancers." (PMID 38542205, 2024). "The human family of MYB transcription factors comprises MYB (c-MYB), MYBL2 (b-MYB), and MYBL1 (a-MYB), which are overexpressed in several cancers and are associated with cancer progression and resistance to anticancer drugs." (PMID 38835346, 2024).
cancer (continued). "MYB, known for its overexpression in cancer tissues, modulates stem cell properties and cell growth in cancers through the regulation of MiR-143." (PMID 38255993, 2024). "Research indicates that MYB proteins play a crucial role in supporting cancer cell survival, thereby constituting a major obstacle in cancer therapy." (PMID 39139556, 2024). "Substantial amounts of data document the association of c-MYB and MYBL2 in a variety of cancers, including breast cancers, compared to fewer studies describing the involvement of the MYBL1 gene in cancer processes." (PMID 38473786, 2024). "The MYB (myeloblastosis) family of transcription factors has meanwhile also garnered increased importance as a driver of cancer progression and resilience." (PMID 38835346, 2024). "MYB is a direct target of Estrogen signaling and is overexpressed in most ER+ cancers, and both genes were also identified as part of a luminal expression signature." (PMID 38603606, 2024). "A detailed understanding of the effects of MYB proteins on drug resistance enables a proper adjustment of established cancer therapies and the design of new and more efficient therapies." (PMID 38835346, 2024). "We suggest that, in BPDCN, and potentially in other cancers, MYB contributes to cell cycle dysregulation by binding to and activating G2/M cell cycle genes using DNA motifs normally targeted by B-MYB." (PMID 39499902, 2024). "Many studies have reported that abnormal MYB expression affects cancer cell expansion, differentiation, and apoptosis." (PMID 38956026, 2024). "Because of its role in oncogenesis, MYB is now a compelling target for therapeutic interventions in cancer research." (PMID 38542205, 2024). "Recent work has identified the role of MYB in the hypoxic survival of the cancer cells, mediated by its ability to stimulate HIF1a expression and function." (PMID 38542205, 2024). "Cluster 1 genes enrichment was for just one GO term, transcription regulator complex, and included genes for the cancer-associated transcription factors RUNX1, HOXA9, and MYB." (PMID 38165902, 2024). "Apart from the critical role of MYB in cancer as an oncogene, MYB also affects the immune microenvironment." (PMID 36994664, 2023). "We then utilized the TISIDB database to clarify the relationship between immune and molecular subtypes and MYB expression in different cancers." (PMID 36994664, 2023). "Meanwhile, MYB expression was positively or negatively related with the prognosis in different cancer types." (PMID 36994664, 2023). "Although we have comprehensively exhibited the prognostic and immunological roles of MYB in pan-cancer, we have to admit that some limitations still remain in our study." (PMID 36994664, 2023). "Our bioinformatic analysis unexpectedly identified MYC signaling as an alternative pathway for cancer cell proliferation upon the knockdown of both MYB and NOTCH1." (PMID 36879115, 2023). "According to our analysis, in a series of cancer types the expression level of MYB is significantly related to immune score and in approximately a half of these cancer types the MYB expression is positively related to immune score." (PMID 36994664, 2023). "Meanwhile we used TIMER 2.0 database, which is based on TCGA database to verify the expression of MYB in different cancers." (PMID 36994664, 2023). "We downloaded data from UCSC Xena database and explored the expression of MYB and two types of immune checkpoint genes, including 24 inhibitory genes and 36 stimulatory genes in 40 human cancers." (PMID 36994664, 2023). "To further study the relationship between MYB and cancers, we identified the mRNA expression level in different tissues using several databases." (PMID 36994664, 2023). "We used TCGA database to obtain the expression patterns of MYB in cancers and paraneoplastic tissues." (PMID 36994664, 2023). "This analysis points to a specific context–dependent function of MYB in modulating cancer progression." (PMID 37478172, 2023).
cancer (continued). "While the expression of MYB is significantly lower in only 5 cancers including HNSC, SKCM, PCPG, ACC and KICH." (PMID 36994664, 2023). "Based on our pan-cancer analysis of MYB, we found that MYB was differentially expressed between tumors and normal tissues, and there was a connection between MYB expression and prognosis." (PMID 36994664, 2023). "In a total of 38 types of human cancer, MYB expression had a significant relationship with cell infiltration in 31 types of human cancer." (PMID 36994664, 2023). "Duplications overlapping MYB span the gene and the evidence of ecDNA events in four patients (CN = 5–45) support its role as an oncogene as identified in other cancer types." (PMID 35396535, 2022). "MYB is the first discovered proto-oncogene located in 6q22-23, which has strong carcinogenic effect and is known to be expressed in a variety of malignant tumors." (PMID 35331206, 2022). "Our new findings thus offer a potentially safe alternative to the drug toxicity of MYB-inhibitors, considering the time-tested safety and recently reported anti-cancer efficacy of these nutraceuticals." (PMID 35600365, 2022). "Taken together, these data suggest that MYB plays an important role in cancer progression and metastases through regulation of cellular apoptosis, and this gene is critically involved in the anti-tumorigenic effects of the combined treatment with BBR and OPCs." (PMID 35600365, 2022). "Breast, ovarian, colorectal, and colon carcinoma are all examples of cancers where MYB plays a key role in cancer generation and development." (PMID 36005140, 2022). "In WT mice, GEM responses are driven by metabolic regulators (primarily lipid metabolism), while in Rag1KO mice, CPA and GEM responses are driven by chemical drivers, and cancer associated drivers were inhibited (MYC, SOX4, MYB)." (PMID 35309309, 2022). "According, in support of several previous reports and our results of siRNA experiments in this study, MYB played an important role in cancer progression and metastases through regulation of apoptosis." (PMID 35600365, 2022). "In this study, we for the first time report that MYB is critically involved in the anti-tumorigenic effects for the observed anti-cancer effects with BBR and OPCs." (PMID 35600365, 2022). "More specifically, MYB has also emerged as an attractive therapeutic target in cancers, and several small molecules or peptide-mimetic inhibitors have shown promise as anti-cancer agents." (PMID 35600365, 2022). "The use of modern molecular biology and gene modification methods in vitro and in vivo over the last decade has shown the significance of c-MYB in several forms of cancer." (PMID 36005140, 2022). "Posttranscriptional regulation of MYB via miRNA-mediated mechanisms has been demonstrated in multiple cancer cell types and during the cellular differentiation." (PMID 36410437, 2022). "The role of MYB in the biology of prostate and other cancers has been demonstrated by us and others." (PMID 36410437, 2022). "The carcinoma harbored a MYB rearrangement as detected by in situ hybridization and lacked ER, PR and HER2 expression by IHC." (PMID 35953528, 2022). "In laryngeal squamous cell carcinoma (LSCC), YB-1 induces miR-155 expression through MYB and promotes cancer development." (PMID 34876130, 2021). "ZFAS1 and MAFG-AS1 act as molecular sponges for miR-150, resulting in downregulation of miR-150 and upregulation of MYB in cancers." (PMID 34876130, 2021). "Many miRNAs show reduced levels in cancer, the inhibition of MYB by these miRNAs is removed, and the expression of MYB is upregulated." (PMID 34876130, 2021). "In human LSCC, YB-1 transcription factors promote the invasion and migration of cancer cells through MYB-induced miR-155 expression." (PMID 34876130, 2021). "Considering the pathological role of MYB oncoproteins towards cancer, functional and structural analysis of MYB oncoproteins still remains vague." (PMID 34921182, 2021).